IL1B (interleukin 1 beta)
Diseases named in the same sentence as IL1B in open-access papers (continued):
Sharing a sentence is not in itself a finding about the gene and the disease.
COVID-19 (continued). "We also discuss the therapeutic relevance of targeting IL-1β to improve COVID-19-related outcomes." (PMID 36209522, 2022). "COVID-19 patients have high levels of proinflammatory cytokines, including interleukin (IL)-1β, IL-6, IL-8, interferon-gamma (IFNγ), 10 kD interferon-gamma-inducible protein (IP-10), and monocyte chemoattractant protein-1 (MCP-1, CCL-2), which probably activate T-helper-1 (Th1) cell responses." (PMID 36294868, 2022). "Taken together, levels of IL-6, IL-8, and IL-10 were associated with the disease severity of COVID-19, and levels of IL-1β, IL-6, and IL-8 were correlated with the prognosis of COVID-19 patients, which may be used to predict the disease severity of COVID-19." (PMID 35540724, 2022). "Thus, our results demonstrated for the first time that exosomes from COVID-19 plasma trigger NLRP3 inflammasome in endothelial cells of distant organs resulting in IL-1β secretion and inflammatory response." (PMID 35587188, 2022). "We found that serum concentrations of IL-1β (p = 0.0086) and IL-18 (p = 0.0025) were significantly higher in patients with severe COVID-19 as compared with those suffering from mild-to-moderate COVID-19." (PMID 34997207, 2022). "The genes, including IL6, IL1B, and TNF, encode inflammatory cytokines of CRS in COVID-19." (PMID 35979235, 2022). "Therefore, we linked comparably elevated IL1B and CXCL8 values to the emerging role of neutrophil activation in both KD and severe COVID-19." (PMID 36159873, 2022). "The earliest reports of COVID-19 clarified that IL-1β, IL-6, TNFα, and CCL3 in the peripheral blood of patients with severe COVID-19 pneumonia were significantly higher than those of non-severe patients, and this cytokine storm is an important factor contributing to death from COVID-19." (PMID 35120332, 2022). "Moreover, higher expressions of epithelial cell-derived IL-6 and myeloid-derived IL-1β in lung tissues are distinguishing features of COVID-19 compared with healthy controls, influenza pneumonia, bacterial pneumonia, and acute respiratory distress syndrome." (PMID 35248063, 2022). "Increased plasma IL-6, TNF-α, and IL-1β are characteristic of severe COVID-19 patients." (PMID 36298628, 2022). "When cytokine levels were evaluated in the culture media of PBMCs derived from healthy individuals and COVID-19 patients, a higher tendency to secrete cytokines such as IL-1b, TNF, IL-6, INFg, IL-17, MCP-1, and IL-10 was observed in cells exposed to SARS-COV2 infection." (PMID 35831294, 2022). "Adding to that evidence the increased expression of both IL-1β and IL-18, as inflammasome activation products and as inflammasome complex upregulators, corroborate our hypothesis of its activation in COVID-19." (PMID 36361818, 2022). "Interestingly, we found that the lower expression of IFN-λ in the lungs of patients who died because of COVID-19 compared to control was paralleled by a higher expression of IL-1β in the same group." (PMID 36422642, 2022). "Plasma concentrations of IL-1β, IFN-γ, MCP-1 and IP-10 are elevated in COVID-19 patients, which may cause a Th1-type response." (PMID 36307516, 2022). "A recent study comparing the immune profiles of children who recovered fully from COVID-19 and those with long-term symptoms revealed persistently high levels of interleukin (IL)-6 and IL-1β, thus attributing a relevant role to the innate immune response during the post-COVID-19 condition." (PMID 35633949, 2022). "Anakinra, an inhibitor of IL-1, and canakinumab, a half-life-prolonged IL-1β, may have potential benefits in the treatment of COVID-19, for which prospective randomized controlled trials are currently underway." (PMID 36090995, 2022). "It is a possibility that the type I IFNs might be contributing to the hyper inflammation responses by intensifying the inflammation driven by TNF/IL-1β in the severe progression of COVID-19." (PMID 36415655, 2022).
COVID-19 (continued). "Significantly elevated levels of IL-1β modulator, IL-1RA, were found in COVID-19 patients in serum and tracheal aspirate samples, which could partially explain the lower levels of IL-1β in airway compartment." (PMID 35720401, 2022). "Growing evidence suggest that severe COVID-19 patients have higher plasma levels of cytokines, such as IL-1β, IL-6, and IL-10, and concentration of these cytokines in the plasma may differentiate mild, moderate, and severe cases." (PMID 36422492, 2022). "Therefore, additional studies in humans and mouse models are still needed to unravel the role of IL-1β during severe COVID-19." (PMID 35720401, 2022). "With regard to IL-1β, a proinflammatory cytokine that is activated and secreted upon the activation of the inflammasome, it has been observed in the peripheral blood of patients with COVID-19-induced pneumonia." (PMID 35330391, 2022). "Furthermore, COVID-19 exosomes significantly induced mature IL-1β secretion in both HMEC-1 and TMNK-1 endothelial cell culture medium." (PMID 35587188, 2022). "Similarly, SARS-CoV-2 N protein promotes NLRP3 inflammasome activation (Pan and others 2021), explaining the high levels of IL-1β observed in COVID-19 patients (Rodrigues and others 2021)." (PMID 35674675, 2022). "In COVID-19, activation of TLRs lead to activation of inflammasome, production of IL1β and IL-6." (PMID 36202985, 2022). "Furthermore, IL-1β mediates Il-6 synthesis, a key proinflammatory cytokine in COVID-19 cytokine storm and a potent inducer of CRP." (PMID 36422492, 2022). "In addition, abnormalities in the production of pro-inflammatory cytokines, including the release of IL-1β, were noted in severe COVID-19 cases, which also indicated the impairment of the monocyte’s ability to generate an effective inflammatory response." (PMID 35632823, 2022). "Interestingly we found that lung tissues of severe COVID-19 patients express higher levels of IL-1β and IFN- β and reduced levels of IFN-λ compared to controls." (PMID 36422642, 2022). "Thus, we tested the effect of NSP5, NSP9, and NSP10 on the expression of IFNβ, IL-6, and IL-1β, which are some of the most frequently deregulated cytokines in COVID-19 patients." (PMID 36173315, 2022). "The anti-IL-1β antibody inhibitor canakinumab was also suggested as a viable therapeutic for COVID-19 patients; however, a recent clinical trial investigating its use showed that it did not significantly increase survival without invasive mechanical ventilation." (PMID 35265086, 2022). "In addition to IL-1β, circulating levels of IL-1Ra, IL-18 and IL-18 binding protein (IL-18BP) are increased in hospitalized COVID-19 patients." (PMID 36209522, 2022). "Pneumonia is linked to blood levels of IL-1β, IL-7, IL-8, IL-9, and IL1-5 in COVID-19." (PMID 36111104, 2022). "Among inflammatory markers associated with COVID-19 mortality, there was a significant interaction between the Non-Hispanic Black population and interleukin-1-beta (interaction p-value 0.04)." (PMID 35350196, 2022). "Moreover, we observed that proinflammatory cytokines involved in lymphocyte and macrophage activation (IL-1β, IL-6, IL-16), Th2 (IL-4), and Th17 (IL-17A) responses were also increased in urine samples of COVID-19 patients." (PMID 36359444, 2022). "Also, IL-1β levels were found to be increased in mild-moderate COVID-19 patients that were restored in severe patients." (PMID 35529862, 2022). "Another potential target in COVID-19 therapeutics can be IL-6 induced by IL-1β." (PMID 36187170, 2022). "In parallel, these observations have suggested that the NLRP3 inflammasome and IL-1β may aid the innate immune memory after recovery from COVID-19 and contribute to the immunogenicity of SARS-CoV-2 vaccines." (PMID 36209522, 2022).
COVID-19 (continued). "To assess the general landscape of immune perturbation in different clinical settings of COVID-19, we contemporary measured the concentration in peripheral blood of six cytokines involved in the inflammation orchestrating: IL-6, IL-1β, IL-17A, TGF-β, TNF-α and IFN-γ." (PMID 35508575, 2022). "Namely, COVID-19 patients had higher levels of IL-1β and T lymphocyte activation (including IL-7), whereas septic shock displayed higher levels of IL-6 and IL-8, and a more significant myeloid response (including triggering receptors expressed on myeloid cells-1 (TREM-1 and IL-1ra)." (PMID 36008932, 2022). "First, tryptophan supplementation or improvement of the tryptophan metabolic pathway may prevent severe COVID-19; second, blockade of IL-6 and IL-1β may prevent severe COVID-19 by protecting against circulatory disturbance caused by thrombosis." (PMID 36035409, 2022). "Exosomes from COVID-19 patients induce maturation and secretion of IL-1β in endothelial cells." (PMID 35587188, 2022). "Recently several reports have highlighted the role of innate immune cells, particularly monocytes, and of monocyte-derived cytokines such as IL-1b, in COVID-19 and showed a correlation between the degree of involvement of innate immunity and disease severity and outcome." (PMID 36096831, 2022). "In addition, high levels of IL-1β and IL-6 were observed in patients with severe COVID-19 than other patients." (PMID 35168674, 2022). "Upon activation, caspase 1 processes pro-IL-1β and pro-ΙL-18 into their functional cytokine forms, which initiate the production of several other cytokines such as IL-6, IL-8, and TNFα, all of them overexpressed in severe COVID-19." (PMID 36498845, 2022). "In patients with moderate disease, the core COVID-19 inflammatory cytokine signature with IL-1a, IL-1b, IL-17A, and IFN-α observed in the first 10 days from symptom onset declined steadily and the same happens with the innate cytokine IL-12, a key inducer of Th1 immune response, as well as IFN-γ." (PMID 35833134, 2022). "Interestingly, the profile of this cluster in COVID-19 again shows a mixed Th1/Th2/Th9/Th17 response, together with innate cytokines (IL-1β, IL-6), eosinophil chemokines (CCL11), growth factors, and vasoactive molecules (GM-CSF, HGF, EGF, VEGF)." (PMID 35674675, 2022). "Indeed, the levels of the major cytokine IL-1β were elevated in the plasma of some COVID-19 patients and IL-1β is a potent inducer of COX-2 expression." (PMID 36226145, 2022). "In the BAL fluid of patients with COVID-19, significantly increased and extremely high levels of the cytokines IL-1β, IL-1RA, IL-17A, TNF-α, and G-CSF and the chemokines CCL7, CXCL1, CXCL8, CXCL11, and CXCL12α were found in comparison with BAL fluid of patients with influenza." (PMID 34793331, 2022). "This cell-host interaction is important as many of the cytokines produced in response to COVID-19 (i.e., interleukin-1 beta (IL-1β), IL-2, IL-6, IL-8, IL-10, and tumor necrosis factor alpha (TNFα)) stimulate infiltration of macrophages, monocytes, and neutrophils into the lung tissue." (PMID 35033181, 2022). "As is known, IL-1β plays an important role in inducing cytokine storm in COVID-19 patients." (PMID 36263178, 2022). "A number of studies have shown that the sign of COVID-19 was the cytokine storm with elevated levels of interleukin-6 (IL-6), IL-1β, complement C1r (C1R), tumor necrosis factor-alpha (TNF-α), chemokine (C-C-motif) ligand 2 (CCL2), and granulocyte-macrophage colony-stimulating factor (GM-CSF)." (PMID 35726234, 2022). "LNT, on the other hand, has strong regulatory effects on IL-1β and IL-6, and some researchers have postulated that it may also regulate COVID-19." (PMID 35669119, 2022). "There is contradicting data about the levels of IL-1β in COVID-19 patients." (PMID 35548445, 2022).
COVID-19 (continued). "In addition, we demonstrated that cells infected with SARS-CoV-2 exhibit high expression of IL-1β and IL-6, both components of the SASP and implicated in systemic features of severe COVID-19." (PMID 35086840, 2022). "High levels of cytokines, such as IL-6, IL-1β, TNF-α, and IFN-γ, have been detected in COVID-19 patients, causing a syndrome called cytokine storm, which is believed to be the main cause of tissue damage in the pathophysiology of COVID-19." (PMID 35062298, 2022). "Multiple cytokines with elevated levels have been identified in COVID-19, including IL-1β." (PMID 35562935, 2022). "One of the key contributing factors for the higher mortality and morbidity in COVID-19 patients is excess local production of pro-inflammatory cytokines, such as IL-1β, IL-6, IL-8 and TNF in key organs (heart, lungs and liver), which is termed a cytokine storm." (PMID 34422917, 2021). "The SARS-CoV-2 S protein promotes NLRP3 inflammasome activation and IL-1β secretion in COVID-19 patient-derived macrophages, and stimulation of the S protein upregulates both IL-1β and TNF-α; however, TNF-α is secreted in an NLRP3 inflammasome-independent manner." (PMID 34360684, 2021). "Besides chemokines, interleukin genes, such as IL1RN and IL1B, were also significantly upregulated in COVID-19 patients." (PMID 33912590, 2021). "We next evaluated whether TNF-α, and IL-1β, two cytokines observed in COVID-19 patients, can decrease KLF2 gene expression." (PMID 34253708, 2021). "Furthermore, receiver operating characteristics (ROC) curve analyses showed that IFN-γ, IL-1β, IL-12p70, G-CSF, and VEGF had the highest diagnostic performance to distinguish severe COVID-19 and pandemic influenza A(H1N1)." (PMID 33995342, 2021). "This prompted the formulation of a hypothesis that a coupled loop created by IL-1β and NETs may lead to excessive damage of the alveoli and pulmonary endothelium observed in patients with severe progression of COVID-19." (PMID 33466589, 2021). "Moreover, in vitro, higher levels of IL-6, TNF-α and IL1-β were released from monocytes derived from COVID-19 patients compared to H1N1 2009 patients." (PMID 34728719, 2021). "In addition, mRNA expression of the pro-inflammatory cytokines TNF and IL1B, which are implied in the progression of COVID-19, were strongly reduced." (PMID 33585804, 2021). "If such a correlation is formed in severe COVID-19 patients, the elevated production of NETs and IL1B could lead to a worse immune outcomes." (PMID 33757410, 2021). "The role of IL-6, IL-1β, and TNFα in those suffering with COVID-19 is somewhat contradictory, with conflicting reports of these markers being linked to both mild disease and more severe cases typified by the occurrence of an inflammatory syndrome and a dysregulated proinflammatory response." (PMID 35222355, 2021). "Direct comparisons between patients with influenza and COVID-19 (including patients from both groups with acute respiratory failure) demonstrate that those with influenza had increased IFN pathway responses and reduced TNF and IL-1β responses compared to patients with COVID-19." (PMID 33575657, 2021). "Our data demonstrate elevated activity of the inflammatory cytokines IL-1β and IL-6 in COVID-19 in blood and tissues and demonstrate the utility of cytokine transcriptional response modules in providing a dynamic readout of the activity of these pathways in vivo." (PMID 33319166, 2021). "Similarly, treatment with anakinra, which is a recombinant IL-1RA known to reduce pro-inflammatory cytokines such as IL-1α and IL-1β, exhibits beneficial effects on patients with COVID-19." (PMID 34360684, 2021). "The use of aaPRP may prevent pulmonary fibrosis in severe COVID-19 patients through the reduction of patients' plasma IL-1β concentration and the amelioration of PaO2/FiO2 ratio." (PMID 34306796, 2021).
COVID-19 (continued). "Importantly, the cytokine profile described in COVID-19-Patients shows large similarities with the cytokine profile of α7nAChRs dysregulated macrophages i.e. massively secreting IL-1β, IL-6, tumor necrosis factor alpha (TNF α) α and IL-18 among others." (PMID 33510335, 2021). "Furthermore, the increased glycolysis also increases the production of IL-1β which contributes to the hyperinflammatory response of COVID-19." (PMID 34240083, 2021). "We considered the possibility that prolonged storage may have resulted in the degradation of mediators, though many other cytokines were elevated in these samples relative to COVID-19 (including IL-1β and vWF-A2)." (PMID 33692097, 2021). "To further investigate the role of these cytokines on T cell phenotype, we also exposed PBMCs isolated from patients with COVID-19 to medium containing their own serum in the presence of blocking antibodies directed against IL-1β, IL-1RA, IL-6, IL-8, or IP-10, added either individually or as a pool." (PMID 34784300, 2021). "P3 and P4 exhibited increased IL-1β production compared to COVID-19 patients." (PMID 34531865, 2021). "In addition, the mRNA level of the inflammasome component NLRP3 and the enhanced production of IL-1β are reversed by treatment with 25-HC@DDAB in PBMCs from patients with severe COVID-19." (PMID 34360684, 2021). "Moreover, severe COVID-19 induces the expression of Tbet that preferentially controls Th1 responses and downregulates the inflammatory cytokines TNFα, IL-1β." (PMID 34512643, 2021). "Importantly, severe cases of COVID-19 are identified as uncontrolled inflammatory response known as cytokine storm where IL-6, IL-1β, IL-10, and IFN-γ have been found to be significantly higher." (PMID 35250966, 2021). "Many of these genes, such as IL1B and its receptors are also highly activated in COVID-19 patients." (PMID 33608566, 2021). "The higher disease severity and mortality of COVID-19 observed in the African American population might be explained—at least in part—by the higher expression of IL-1β, IL-18 receptor, IL-12Rβ1, and some toll-like receptors." (PMID 33996683, 2021). "IL-1β has been reported to be elevated in COVID-19 and correlated with disease symptoms." (PMID 34575258, 2021). "However, together these data suggest that the contribution of IL-6 and IL-1B to cytokine storm in severe COVID-19 is the result of systemic immune dysregulation downstream of the epithelium." (PMID 34867390, 2021). "Pro-IL-1β mRNA was decreased in COVID-19 patients when compared to CONTROL subjects." (PMID 34315957, 2021). "Because IL-6 trans signaling and IL-1β play vital roles in both COVID-19 and HF, their inhibitors may be effective and novel treatments to prevent the progression of HF in patients with COVID-19." (PMID 33404925, 2021). "Interestingly, IL-1β was positively correlated with SOFA scores in COVID-19 patients, but remained negatively correlated in controls." (PMID 34131192, 2021). "Hence, in this study, we explored the effect of intravenous (IV) aaPRP administration on the plasma levels of IL-1β-a profibrotic and proinflammatory cytokine in severe and critical COVID-19 patients." (PMID 34306796, 2021). "Lee and coworkers reported that severe COVID-19 was associated with TNF-α and IL-1β signatures." (PMID 34319784, 2021). "We propose that IL-1β and IL-6 transcriptional response modules provide a dynamic readout of functional cytokine activity in vivo, aiding quantification of the biological effects of immunomodulatory therapies in COVID-19." (PMID 33319166, 2021). "IL-1β levels were lower in COVID-19 patients with neurological disorders (FDR < 0.05)." (PMID 34960684, 2021). "IL-1β and its downstream effectors IL-6 and TNF-α are linked to the exacerbation of COVID-19." (PMID 34150848, 2021). "The characterization of COVID-19 pathophysiology highlighted the decisive role of IL-1β and IL-6." (PMID 34012390, 2021).